CRP (C-reactive protein)
Diseases named in the same sentence as CRP in open-access papers (continued):
Sharing a sentence is not in itself a finding about the gene and the disease.
Sepsis (continued). "Higher CRP levels have been shown to indicate a more severe disease status and a worse prognosis in patients with sepsis." (PMID 39252713, 2024). "We assessed six biomarkers for their effectiveness in predicting sepsis in ICU admissions: CRP, RDW, NLR, MDW, MNV, and MMV." (PMID 39776743, 2024). "Our study highlights an association between elevated levels of CRP and the NLR with an increased risk of developing sepsis in patients diagnosed with UROP." (PMID 39064542, 2024). "The WBC count, neutrophil percentage, PCT level, and CRP level in patients with sepsis were elevated beyond the normal range, and inflammation occurred." (PMID 38213768, 2024). "Criteria for sepsis were verified in 77 patients (36%) and septic shock in 20 (9.3%), with no statistical difference when comparing the groups with good and poor CRP responses." (PMID 39272020, 2024). "MDSCs show potential as a diagnostic biomarker comparable to CRP and PCT, in infection and sepsis, even in distinguishing sepsis from infection." (PMID 38609858, 2024). "Serum lactate, albumin, lactate/albumin ratio, C-reactive protein, platelet levels, and three sepsis severity scales, (CCI, SOFA, APACHE IV) were assessed." (PMID 38576552, 2024). "Procalcitonin (PCT), the propeptide of calcitonin, emerged as a biomarker for sepsis because of its sensitivity and specificity, reported to be higher than those of CRP." (PMID 38256033, 2024). "This systemic inflammation, often observed in conditions such as sepsis, is characterized by elevated levels of inflammatory markers like C-reactive protein (CRP), interleukin-6 (IL-6), and tumor necrosis factor-alpha (TNF-α)." (PMID 39563441, 2024). "In line, patients developing arrhythmia during sepsis had higher levels of C-reactive protein (CRP)." (PMID 38099844, 2024). "Other studies demonstrated significantly higher leucocyte counts and CRP levels at admission in trauma patients with sepsis." (PMID 38541796, 2024). "Laboratory parameters that present significant modifications in sepsis include lactate, CRP, cytokines, D-dimers, proadrenomedullin (ProADM)." (PMID 38804397, 2024). "CRP serves as an outcome predictor for various diseases like infection, sepsis, cancer, heart failure, and postoperative conditions." (PMID 38791046, 2024). "CRP serves as a valuable biomarker in the prompt identification of sepsis, boasting a high degree of sensitivity, yet indicating restricted specificity." (PMID 39201697, 2024). "IL-6 and IL-10, which have better predictive ability for sepsis among all immune response biomarkers, as well as CRP, PCT and clinical scores were selected for further analysis of their relationship with secondary endpoints." (PMID 39212218, 2024). "We found that deceased patients with sepsis secondary to BSI have significantly elevated levels of CRP (mean CRP: 199 mg/L) within 24 hours of blood culture collection." (PMID 39252713, 2024). "The results of this study indicate that larger decreases in the levels of PCT, CRP, and LAC over the first 72 h are associated with improved survival in sepsis patients." (PMID 39272757, 2024). "While there are limited data on the prognostic role of these biomarkers, some studies have emphasized that changes in PCT and CRP levels can be indicative of the outcome of sepsis." (PMID 39459346, 2024). "While CRP and ratios like CRP and CAR provide valuable insights into the risk of neonatal sepsis, the inflammatory markers investigated in the current study offer a broader diagnostic scope by considering multiple physiological parameters." (PMID 38790588, 2024). "The remaining investigations showed hypoalbuminemia, elevated sepsis marker (C-reactive protein (CRP)=57 mg/L), and positive Bence-Jones protein in the urine." (PMID 39735127, 2024). "The investigation of CRP, PCT, WBC and body temperature for diagnostic purposes with sepsis mimics as the control group has relevance to the research methodology." (PMID 38280062, 2024).
Sepsis (continued). "Patients with ALI were older (p = 0.023), had higher ASA scores (p = 0.031), preoperative CRP concentrations (p = 0.011), incidence of kidney failure (p = 0.002) and sepsis (p = 0.026)." (PMID 38534633, 2024). "In the four studies analyzing a combination of IL-6 and CRP at sepsis suspicion, cut-off values ranged from 21.7 to 60 pg/mL and 4.05 to 14 mg/L, respectively, sensitivities ranged between 78.12 and 100% and specificities between 41 and 96%." (PMID 38671704, 2024). "Plasma concentrations of CRP in healthy individuals are nearly undetectable but are elevated in burn patients with infections or sepsis." (PMID 39716257, 2024). "Serum GRN levels in sepsis exhibited positively correlation with inflammatory factors including hypersensitive C-reactive protein and procalcitonin." (PMID 38166912, 2024). "The use of CRP as a biomarker to help diagnose and treat sepsis has been documented in many studies." (PMID 39416748, 2024). "Numerous studies comparing PCT and CRP in inflammatory diseases and their complications, such as sepsis, chronic obstructive pulmonary disease (COPD), bacterial meningitis, and febrile neutropenia in children, have reached the same conclusion." (PMID 39618643, 2024). "In patients presenting to the emergency department with suspected infection and sepsis, leukocyte, CRP, and PCT levels, when evaluated in combination with clinical severity scores, have been shown to be reliable biomarkers for prognosis." (PMID 39459346, 2024). "C-reactive protein had modest discriminatory power (AUROC 0.71) with confirmed sepsis as the outcome." (PMID 38280062, 2024). "Studies have shown that PGPE has a nephroprotective effect in sepsis and reduces renal function parameters as a consequence of the reduction in CRP levels." (PMID 39459616, 2024). "As prognostic markers, both lymphocyte count and CRP level have been extensively studied in various clinical contexts, including sepsis, cancer, and critical illness following ICU admission." (PMID 39685802, 2024). "This study underscores the superiority of procalcitonin over CRP as a predictive indicator for pediatric sepsis, particularly in assessing the severity and clinical management needs." (PMID 39184737, 2024). "Despite negative blood cultures and β-D-glucan tests, the patient’s significant neutropenia, elevated CRP levels, and high fever raised concerns for possible Candida sepsis." (PMID 39610630, 2024). "The AUC/ROC analysis for MDW performance in detection of sepsis and septic shock according to Sepsis-3 criteria was 0.856 (95% CI 0.82–0.89), slightly below CRP and PCT [0.915 (95% CI 0.89–0.94); 0.872 (95% CI 0.83–0.92) respectively]." (PMID 38956252, 2024). "IL-6 was found to be superior to CRP in the prediction of sepsis 1 or more days before clinical diagnosis." (PMID 38671704, 2024). "Markedly elevated inflammatory markers such as CRP concentrations can serve as a vital indicator, directing attention towards the possibility of septicemia or the presence of an occult abscess, facilitating prompt imaging and accurate diagnosis." (PMID 39020267, 2024). "Our objective was to conduct an individual patient-level systematic review of existing data to assess the performance of PSP compared to PCT and CRP for sepsis diagnosis in the ICU." (PMID 39416748, 2024). "Combining the sensitive IL-6 (cut-off of 30 pg/mL) with the more specific CRP, sensitivity and specificity for sepsis prediction improved to 100% and 96%." (PMID 38671704, 2024). "Septic biomarkers, including procalcitonin (PCT), C-reactive protein (CRP), and IL-6, have been identified for clinical diagnosis and management of sepsis." (PMID 39703795, 2024). "The ability of C-reactive protein (CRP) as a marker of late-onset sepsis (LOS) remains controversial in literature." (PMID 38970042, 2024). "Other cardio-metabolic traits were also identified to have causal effects on sepsis such as type 2 diabetes, HDL cholesterol, CRP, and coronary artery disease." (PMID 38459230, 2024).
Sepsis (continued). "Although traditional biomarkers such as white blood cell count (WBC) and C-reactive protein (CRP) are widely used in diagnosing sepsis, they have certain limitations, such as delayed reflection of condition changes and insufficient specificity." (PMID 39876908, 2024). "It correlates positively with several inflammatory biomarkers, including CRP, IL-6 and TNFα, and has been investigated as a marker of kidney- and heart- injury, as well as sepsis." (PMID 38398274, 2024). "Our study found that the recovery of CD5+ B cell populations favors survival in patients with sepsis, and that the proportion and absolute number of these cells was negatively associated with APACHE II and CRP levels." (PMID 39359725, 2024). "HDL itself correlates with the survival rate of sepsis patients, and low S1P levels in plasma are predictive of septic shock in a more sensitive and specific way than CRP." (PMID 39524325, 2024). "Mean qSOFA scores, a measure of severity in sepsis, were comparable between the groups (10.64 ± 1.86 in C-reactive protein vs. 10.8 ± 1.97 in procalcitonin, p = 0.54)." (PMID 39184737, 2024). "Univariate analysis showed that sepsis, CVL insertion, CRP, and duration of NICU admission were significant risk factors for thrombosis." (PMID 39349608, 2024). "In patients admitted with sepsis, the highest CRP level was seen on day 2 (median 167 (IQR 109–256) mg/l)." (PMID 37204560, 2024). "CRP, a well-known and relatively inexpensive inflammatory biomarker, has been used consistently in the context of adult and neonatal sepsis diagnosis." (PMID 39003476, 2024). "nCD64 has a higher sensitivity and specificity as compared to total leukocyte count, CRP levels, and blood culture sensitivity test in the diagnosis of sepsis." (PMID 39429998, 2024). "PSP of ≥50 ng/L, PCT of ≥12.5 mg/dL, and CRP of ≥155 mg/dL were used as cut-off values to confirm sepsis." (PMID 39295616, 2024). "Commonly used biomarkers for sepsis diagnosis, including C-reactive protein, procalcitonin, and interleukin-6, lack specificity for infection." (PMID 38396935, 2024). "PCT, CRP, and leukocyte count are among the most commonly used biomarkers to predict sepsis and septic shock." (PMID 39459346, 2024). "The AUC for maternal serum iron change as a single metric predictor of neonatal early-onset sepsis was 0.521, significantly lower than the AUC for CRP and white blood cell count (0.662 and 0.576, respectively)." (PMID 39092027, 2024). "To further confirm the prognostic role of PD-1+NK cells in sepsis, we compared the predictive performance between PD-1+NK cells and commonly used inflammatory markers, including CRP, PCT, IL-6, as well as SOFA score." (PMID 38953031, 2024). "The objective of this study was to evaluate the early diagnostic accuracy and prognostic significance of CRP and PCT in patients with sepsis." (PMID 39469363, 2024). "While CRP and PCT remain the most widely used biomarkers in patients with sepsis, level of change and time course for associated mortality have yet to be fully elucidated." (PMID 38684973, 2024). "As expected, TREM2 expression decreased in parallel with the gradual decline of CRP levels, suggesting a strong association of TREM2 with the severity of sepsis patients." (PMID 39405126, 2024). "Among the clinical characteristics, a higher blood value of the infection marker CRP in patients with sepsis than SIRS was the only significant patient subgroup difference in the qRT-PCR subcohort." (PMID 39434093, 2024). "Procalcitonin can be used for the early diagnosis of sepsis in children, and the combination of white blood cell count with CRP and PCT measurements can improve the diagnosis accuracy of bacterial infection in children." (PMID 38827220, 2024). "The important risk factors associated with sepsis during hospitalization were the levels of ALB, CRP, and WBC." (PMID 38771840, 2024).
Sepsis (continued). "Sepsis work-up showed elevated serum CRP levels; therefore, empirical antibiotic therapy was started again with meropenem and amikacin." (PMID 40584606, 2024). "They found that higher CRP-NLR scores were significantly associated with severe outcomes, such as an increased incidence of sepsis in more severely infected patients (22.2% vs. 7.4%, p-value = 0.030)." (PMID 39767619, 2024). "While CRP remains useful and widely available, procalcitonin's enhanced reliability makes it a better choice for predicting severe sepsis outcomes." (PMID 39184737, 2024). "The current diagnosis of sepsis relies on clinical evaluation, blood or urine cultures, and detection of inflammatory response biomarkers such as C-reactive protein (CRP), procalcitonin (PCT), and interleukin 6 (IL-6)." (PMID 38637839, 2024). "In a previous meta-analysis, the sensitivity and specificity were 0.80 (95% CI, 0.63–0.90) and 0.61 (95% CI, 0.50–0.72), respectively, for the diagnosis of sepsis using CRP, and 0.80 (95% CI, 0.69–0.87) and 0.77 (95% CI, 0.60–0.88), respectively, using PCT." (PMID 37147598, 2023). "The median white blood cell count, neutrophil percentage, procalcitonin level, and C-reactive protein level in the sepsis group were higher than those in the non-sepsis group." (PMID 37671148, 2023). "There were significant differences between survivors and non-survivors about feeding, vaccination status, presence of previous admission, heart failure, sepsis, thrombocytopenia, anemia, and positive CRP." (PMID 37542670, 2023). "This study seeks to analyze IL-6 behavior in suspected early-onset sepsis (EOS) cases among term newborns, comparing it to that of CRP and evaluating IL-6’s diagnostic utility." (PMID 38255366, 2023). "Currently, the markers used in clinical practice to support the diagnosis of sepsis are CRP and procalcitonin (PCT), but they have limitations." (PMID 37509475, 2023). "In this cross-sectional analytical study, the bedside rapid salivary CRP estimations were found to be a good predictor of culture-positive sepsis in neonates with suspected sepsis." (PMID 36900011, 2023). "The use of nanoparticles was found to facilitate the quantification of various sepsis biomarkers (CRP, IL-6, and PCT) as well as the detection of both Gram-positive and Gram-negative bacteria in whole blood samples." (PMID 37376129, 2023). "Second, the serum IL-36 family member's levels were related to the severity of sepsis, including CRP, PCT, and SOFA scores." (PMID 38093296, 2023). "Although CRP is commonly used for early diagnosis of sepsis in several studies, we were unable to concurrently measure CRP and PCT according to the health insurance-related restrictions in Vietnam." (PMID 37189528, 2023). "The findings indicate that the sepsis group exhibited significantly higher scores in body temperature, C-reactive protein (CRP), procalcitonin (PCT), blood urea nitrogen (BUN), SOFA, and APACHE II compared to the control group (p < 0.05)." (PMID 37752563, 2023). "PCRS: by a sepsis workup including ≥2 of the following: complete blood count with differential, CRP, blood culture, urine culture, CSF culture, or antibiotics given for more than 48 h within 72 h of CVCs removal." (PMID 38259593, 2023). "Secondly, we utilized MVMR to assess the independent impact of CRP on sepsis, which was independence of gut microbiota." (PMID 37662942, 2023). "We compared estimated serum calprotectin levels to serum procalcitonin levels and conventional sepsis markers (leucocyte count, blood culture, immature to total neutrophil ratio, and C- reactive protein)." (PMID 37600908, 2023). "This study aimed to test the efficacy and performance of a novel rapid bedside test for the quantitative estimation of salivary CRP by lateral flow assay in newborns with suspected sepsis, bypassing these previous limitations." (PMID 36900011, 2023).
Sepsis (continued). "It combines measures of systemic inflammation (CRP), immune dysregulation (normo- or hypothermia during sepsis) and organ dysfunction (GCS score and bilirubin)." (PMID 37841294, 2023). "For neonatal sepsis, the sensitivities and specificities of CRP in diagnosing sepsis ranged from 29% to 100% and from 6% to 100%, respectively." (PMID 37197571, 2023). "PSP also proved superior to CRP, ferritin, and fibrinogen in sepsis diagnosis, treatment escalation, and readmission prediction with an AUC of 0.862, 0.698, and 0.899, respectively." (PMID 37894237, 2023). "Using a cutoff level of 6.2% for the DNI, this marker was found to be superior in predicting sepsis-related mortality compared with other markers, such as CRP and procalcitonin." (PMID 38137411, 2023). "The optimal cutoff value of CRP for predicting death was 31 mg/L in patients with sepsis, which was between the 3rd and 4th quartile values of CRP (28.2 mg/L and 40 mg/L, respectively)." (PMID 36832265, 2023). "The WBC, uric acid and CRP values of the patients in the control group were found statistically significantly lower than those of the proven and clinical sepsis groups." (PMID 37398776, 2023). "Current sepsis biomarkers, including lactate, C-reactive protein (CRP), and procalcitonin (PCT) can be used to determine organ failure and evaluate the patient’s clinical course." (PMID 37537685, 2023). "In our study, the serum concentration of CRP acted as the most important feature for diagnosing sepsis with the importance value of 0.37." (PMID 36834338, 2023). "In the study population, the serum and salivary CRP cut-off scores for predicting culture-positive sepsis were 2.8 mg/dL and 11.6 ng/mL." (PMID 36900011, 2023). "There is limited information on the use of CRP, procalcitonin, and presepsin to predict survival in critically ill patients with sepsis undergoing CRRT." (PMID 36832265, 2023). "A comparison of sepsis markers was done on the basis of CRP levels, N:L ratio, procalcitonin levels, and serum albumin levels." (PMID 38058329, 2023). "Serum C-reactive protein (CRP) is an acute-phase reactant that is commonly used in conjunction with other parameters in a sepsis screen." (PMID 36900011, 2023). "An increase in CRP expression was observed in inflammatory conditions such as rheumatoid arthritis, cardiovascular diseases, cancer and sepsis." (PMID 37465171, 2023). "According to the reviewed research articles, MIP-based biosensors can be applied for inflammation and sepsis biomarkers, such as human serum albumin, C-reactive protein, serum amyloid A, tumor necrosis factor-alpha (TNF-α), procalcitonin, IL-6, and IL-1β." (PMID 37366985, 2023). "Regarding the evaluation of CRP performance for the discrimination of sepsis severity, a significant difference was observed between sepsis and septic shock subgroups (12.7 [5.3; 18.3] mg/dL vs. 18.7 [17.3; 27.9] mg/dL, p = 0.018)." (PMID 37238265, 2023). "The rapid bedside assessment of salivary CRP appears to be an easy and promising non-invasive tool in culture-positive sepsis prediction." (PMID 36900011, 2023). "This explains why results are conflicting and why, together with studies showing adequate sensitivity and/or specificity, several studies report very poor accuracy of CRP for early sepsis identification." (PMID 37627653, 2023). "Multivariate analysis considering all factors affecting plasma adiponectin levels in males or females identified BMI in females and CRP levels in males to predict plasma adiponectin levels in SIRS/sepsis patients." (PMID 38137508, 2023). "We found that CRP, procalcitonin, and presepsin can discriminate sepsis with statistical significance." (PMID 36832265, 2023). "The aim of this study was to retrospectively evaluate sepsis’ diagnostic performance of NEUT-RI as compared with PCT and CRP." (PMID 37238265, 2023).